MUC2 (mucin 2, oligomeric mucus/gel-forming)
Diseases named in the same sentence as MUC2 in open-access papers (continued):
Sharing a sentence is not in itself a finding about the gene and the disease.
infection (continued). "BALB/c mice were infected with HMPV, and the expression of Muc1, Muc2, Muc4, Muc5ac, Muc5b, Muc15, Muc16, Muc19, and Muc20 were analyzed at 12, 24 and 48 h after infection." (PMID 32899224, 2020). "Expression of MUC2 and Occlaudin were significantly downregulated (p < 0.05) in the MC group compared to the CK group, which suggested that infection of E. coli O157 suppressed the expression of part of the protein related to gut barrier function." (PMID 33233359, 2020). "Inflammatory lesions can reduce goblet cells, which produce mucin and contain the MUC2 gene, prevent the mucosal layer from replenishing and increase the chance for further infection, bacterial translocation and inflammation in the intestine." (PMID 33088501, 2020). "Our results show that prior long-term exposure to long-day (PLD, 16 L : 8 D) photoperiods modified the expression of mucosal muc2 in skin tissues and the Treg cytokine foxp3a in the spleen and skin tissues in response to infection with G. gasterostei." (PMID 32605431, 2020). "Modelling each immune variable by final parasite burdens demonstrated that fish with lower muc2 expression in skin tissues harboured significantly greater infections (GLM, F′1,32 = 4.68, p = 0.038)." (PMID 32605431, 2020). "This suggests that photoperiod history not only modulates baseline muc2 expression in skin tissues, but also affects the way in which expression of this gene responds to infection." (PMID 32605431, 2020). "S. flexneri is able to replicate intracellularly in enteroids derived from different segments of the human intestine, and infection resulted in increased production of the mucin glycoprotein Muc2 and increased secretion of IL-8." (PMID 30642900, 2019). "Recent studies showed a drastic decrease in Muc2 production by enteroids upon infection with enterohemorrhagic E. coli (EHEC)." (PMID 30642900, 2019). "In this study, we show that infection with WT S. flexneri results in increased expression of the mucin glycoprotein Muc2 at 4 h postinfection." (PMID 30642900, 2019). "Infection with the nematode C. oncophora results in increased mRNA and protein levels of Muc2 in the small intestine." (PMID 29912166, 2018). "Lastly, a recent study showed that infection with GS isolate depletes mucus throughout the small and large intestines, in human biopsies and in mice, and indices muc2 and muc5 gene expression in mice." (PMID 30062089, 2018). "Failure of crypt cells to differentiate into goblet and absorptive cells results in a severe decrease of MUC2 glycoprotein in the affected epithelium at the peak of infection." (PMID 30140680, 2018). "Despite the difference in infection model, the up-regulation of muc2 gene shown here was consistent with that in mice model and demonstrates a general effect of GS isolate infection on the mucus layer." (PMID 30062089, 2018). "In the present study, the RV-stimulated MUC2 production in the small intestine was probably due to an attempt to control the infection." (PMID 30406046, 2018). "As microbiota colonizes and utilizes MUC2 mucin substrates as a food source to maintain homeostasis, it stands to reason a delicate balance must exist to sustain asymptomatic Eh infections." (PMID 30500860, 2018). "Further, realtime RT-PCR indicated that infection significantly reduced Muc2 mRNA in the ileum of GC-C−/− mice relative to WT animals." (PMID 29367634, 2018). "Consistent with previous reports we have confirmed the specific depletion of goblet cell-derived MUC2 at the peak of infection." (PMID 28323899, 2017). "Re-challenging these chronically infected mice with a high dose infection resulted in the induction of Muc2 and Il13 expression and a reduction in Ifnγ expression." (PMID 28192541, 2017). "In the mice with acute infection, as infection progressed, there was goblet cell hyperplasia and the expected increase in Muc2 expression." (PMID 28192541, 2017).
infection (continued). "More recently, it was reported that mice with an IEC-specific deletion of MyD88 display defects in Muc2 expression and crypt antimicrobial capacity in the cecum during the early phase of infection with C. rodentium." (PMID 28520792, 2017). "In this study, the mRNA expression of MUC2 appeared significantly downregulated upon infection but significantly increased again after treatment with PPE." (PMID 25654088, 2015). "The infection up-regulated the expression of resistin-like molecule beta (Retnlb), angiogenin 4 (Ang4), and mucin 2 (Muc2) but down-regulated regenerating islet-derived protein 3 gamma (Reg3γ) and lysozymes 1 (Lyz1) and 2 (Lyz2)." (PMID 26377648, 2015). "PPE was able to alter this downregulation of MUC-2 due to infection, supporting the contention that PPE has a role in the regulation of goblet cell producing mucin." (PMID 25654088, 2015). "The result of the immunofluorescence staining of Muc2 revealed that mice infected with WT for 16 h have fewer goblet cells expressing Muc2, which was negated by infection with vvpE mutant." (PMID 26086960, 2015). "A large fraction of the E/S components secreted by the parasite during infection is made up of serine proteases that have a documented capacity to degrade the major intestinal mucin, muc2." (PMID 25942314, 2015). "Our qRT-PCR results revealed that the expression of MUC-2 was significantly reduced following infection." (PMID 25654088, 2015). "In this study the authors also analyzed changes in Muc2 expression in WT mice that showed a trend towards an increase in Muc2 mRNA expression at day 6 post infection." (PMID 24386378, 2013). "Up-regulation of Muc2 expression and alteration of mucin structure is observed in the course of infection in a murine model of rotavirus infection." (PMID 25436881, 2013). "The mRNA expression of TLR4 is significantly upregulated, whereas the expression of MUC2 is significantly downregulated upon infection." (PMID 24367242, 2013). "For instance, increased Muc2 production in the intestine during infection with Trichuris muris was observed only in resistant mice and it was correlated with worm expulsion." (PMID 21569362, 2011). "Since we did not detect any significant phenotypic differences between C57BL/6 and Muc2+/+ mice following infection, we will subsequently refer to these mice as wildtype (WT) mice." (PMID 20485566, 2010). "Our studies reveal novel yet fundamental insights into how Muc2 is used by the host to control infection by an A/E bacterial pathogen." (PMID 20485566, 2010). "We first infected C57BL/6, Muc2+/+ mice and Muc2−/− mice with C. rodentium and monitored body weights and survival over the first 2 weeks of infection." (PMID 20485566, 2010). "We show that the presence of Muc2 and hence the mucus layer is necessary to protect against severe mucosal damage and barrier dysfunction during infection." (PMID 20485566, 2010). "We provide evidence that the ability of Muc2 to control luminal bacteria is most likely attributable to increased Muc2/mucus secretion during infection, which was demonstrated through metabolic labeling of mucin glycoproteins in WT mice." (PMID 20485566, 2010). "However, MUC2 expression levels and goblet cell numbers exhibited a continuous decrease throughout the infection period (6–24 hpi)." (PMID 40797223, 2025). "Notably, MUC5C displayed a delayed but stronger upregulation compared to MUC2, indicating differential regulation of mucin genes during infection." (PMID 41278481, 2025). "The observed upregulation of Muc2 gene expression in CNF1- and CNF1 + DSS-treated animals may reflect an altered production of MUC-2 by goblet cells to protect the gut mucosa from infection." (PMID 39876002, 2025). "Such treatment also reverses the upregulation of mucous layer glycoprotein, MUC2, during infection." (PMID 39170608, 2024).
infection (continued). "Furthermore, mucosal response of mucin-encoding genes (Muc2 and Muc5b) in AS and koi upon CEV genogroup IIa infection in gill, gut and skin tissues was evaluated." (PMID 37465154, 2023). "PAE, based on our results, was able to alter this downregulation of MUC2 due to infection." (PMID 38017513, 2023). "However, the infection with WB+ or WB giardipain-pAC trophozoites for 14 and 21 days and 3 months markedly thickened the layer of MUC2 on the luminal side and increased the number of MUC2-positive cells." (PMID 36362435, 2022). "However, a down-regulated MUC2 gene expression was observed in ETEC F18 infected pigs during the post-peak infection period." (PMID 35990617, 2022). "The reduction of MUC2 secretion may be due to a decrease in the number goblet cells at early infection, however, MUC secretion is increasing with the restoration of immune function and the positive effect of zinc." (PMID 35602082, 2022). "In contrast to the previous experiment, the antibiotic treatment did not result in severe weight loss and mortality of infection-free Muc2−/− mice (100% of mice survived)." (PMID 34639039, 2021). "When chips were harvested prior to epithelial detachment at 15 h after infection instead of 24 h, ZO-1 intensity and the area covered by MUC2 foci were significantly reduced indicating that disruption of tight junctions and decreased mucus accumulation precede epithelial lesion formation." (PMID 33777849, 2021). "In the present study, higher concentrations of thymol nanoemulsion greatly upregulated genes encoding occludin, zona occludens-1, claudins -1, JAM, MUC-2 and FABP2 controlling the barrier functions even after experimental infection, and it was better than thymol." (PMID 33833292, 2021). "It is also possible that the remaining MUC2 observed in goblet cells during infection of colonoids with EAEC could be due to the secretagogue activity of Pic." (PMID 32601325, 2020). "Thus, we suggest that melatonin at 1 μM has a physiological function in the regulation of intestinal MT2 activation and Muc2 production during an infection with V. vulnificus." (PMID 31906951, 2020). "Muc2 is largely produced by goblet cells in the small intestine, and serves as an important structural component of intestinal mucin layer to protect against the infection of luminal viruses." (PMID 31540325, 2019). "Infection with S. Typhimurium SL1344 significantly increased the colonic MUC2 levels." (PMID 30842764, 2019). "MUC2 knockout mice fed with probiotics show resistance to intestinal dysbiosis and infections." (PMID 30140680, 2018). "We observed that butyrate-treated mice challenged with C. rodentium showed differing increases in gene expression of cytokines involved in the clearance of infection (Il17A, Tnfα), the reduction of mucosal inflammation (Tgfβ, Il10), and the improvement of host barrier function (Muc2, Relmβ, Tff3)." (PMID 28861518, 2017). "As expected, infection with E. coli K1 could decrease the MUC2 expression while pre-treatment with LBS was able to reverse E. coli K1-mediated mucin depletion." (PMID 28979247, 2017). "Probiotics have been shown to induce Muc2 and Muc3 mucins and inhibit the adherence of enteropathogenic E.coli suggesting that they may confer protection against infection through alterations in mucin production." (PMID 25436881, 2013). "Microscopy of Muc2 immunostained tissues suggested that the inner striated mucus layer present in the healthy colon was scarce during the time point of most severe infection (10 days post infection), but then expanded, albeit with a less structured appearance, during the expulsion phase." (PMID 24386378, 2013). "This correlates with our observations of an increase in Muc2 transcripts day 4 post infection." (PMID 24386378, 2013). "Moreover, the mRNA expression of TLR4 was significantly upregulated, whereas the expression of MUC2 is significantly downregulated upon infection." (PMID 24367242, 2013).
infection (continued). "However previous studies showed that MUC2 expression can still be modified in the HT29-MTX cell line in response to infection by Escherichia coli." (PMID 22675431, 2012). "Interestingly, GCNT3 mRNA followed the same pattern as MUC2, which were strongly up-regulated only during primary infection, compared to naïve controls." (PMID 21414188, 2011). "Our study shows that Muc2-dependent mucus production is critical for effective management of both pathogenic and non-pathogenic bacteria during infection by an EPEC/EHEC-like pathogen." (PMID 20485566, 2010). "In contrast, in the Muc2-deficient mice there was no decrease in worm burdens until after day 20 after infection, although mice did eventually expel their parasites." (PMID 20138044, 2010). "In contrast, Muc2−/− mice steadily lost weight as their infection progressed." (PMID 20485566, 2010). "However, it is important to note that Muc2 can potentially be modulated in several ways either during infection, such as at the level of gene expression, post-translational modification, or even at the level of secretion into the intestinal lumen." (PMID 20485566, 2010). "Similarly, higher amounts of Muc2 (assessed by Western blotting after agarose gel electrophoresis) were present in the content of mucus collected in the WT mice after infection." (PMID 20138044, 2010). "We observed no discernible PAS-positive goblet cells throughout the cecum of Muc2-deficient mice without infection." (PMID 20138044, 2010). "The observation that the glycosyltransferases are dysregulated after interacting with the miRNAs during infection with C. jejuni supports our hypothesis that a miRNA-dependent modification of the O-glycosylation of MUC2 or other signalling proteins might take place here." (PMID 37848994, 2023). "It has been observed that mucus protein mucin 2 (MUC2) gene expression increases in response to F18+ E. coli infection and is more prolonged during the peak of infection, demonstrating the role of mucin as the first line of defense against infection due to F18+ E. coli." (PMID 37685055, 2023). "Additionally, YL20 could also restore the number of goblet cells, the production of MUC2, and the expression of ZO-1, indicating its protective effect in intestinal barrier function against pathogen infection." (PMID 36145205, 2022). "Importantly, the numbers of goblet cells decreased by WT infection were significantly recovered in the mice group pretreated with 10 mg/kg melatonin, suggesting that melatonin restores Muc2 depletion induced by VvpM in the mouse ileum infected with V. vulnificus." (PMID 31906951, 2020). "Mouse models lacking MUC2 expression are susceptible to intestinal dysbiosis and infections." (PMID 30140680, 2018). "However, after infection we could detect the C. jejuni in the mucus layer, and a few attached to the epithelial surface, which is consistent with the Muc2 mucin forming a mucus barrier protecting the epithelial cells from the majority of bacteria." (PMID 23869232, 2013). "In addition, Muc2 transcription was upregulated 7 days after infection." (PMID 27335862, 2013). "Expression of the major gel-forming mucin—MUC2 and MUC5AC was significantly upregulated by G9P and RVC whereas infection with G5P led to a marginal downregulation of these genes’ expression." (PMID 37848925, 2023). "Existing studies have found that NAD (nicotinamide adenine dinucleotide) can promote the secretion of intestinal mucin 2 (MUC2), enhance the ability of antibacterial infection, and alleviate intestinal inflammation by inhibiting NF-kB." (PMID 37745216, 2023). "During peak infection (5 and 7 dpi), VH and the mRNA abundance of LEAP2, AvBD1, AvBD6, AvBD10, and Muc2 were decreased in infected chickens compared to uninfected chickens." (PMID 36867919, 2023).
infection (continued). "CRKP intestinal colonization resulted in obviously decreased concentrations of TJ proteins and MUC2, whereas CRKP-colonized mice challenged with subsequent translocated infection displayed the lowest concentrations of TJ proteins." (PMID 36445086, 2022). "Hence, the strong correlation between diet-dependent loss of mucus layer resulting from the lack of MUC2, and protection against infection by enteric bacteria is based on the involvement of gut microbiota in forming a protective, impervious, and functional barrier." (PMID 35049768, 2022). "Transcription of genes related to digestion (APN, MCT1, FABP2, and MUC2) were primarily influenced by infection at 7 d PI and tributyrin supplementation (FABP2 and MUC2) at 10 d PI." (PMID 33652244, 2021). "In order to address this and find associated regulatory networks in response to C. jejuni infection, we determined the transcription of MUC2 and TFF3 in the human intestinal epithelial cell line HT-29/B6 following C. jejuni NCTC 11168 infection." (PMID 34183045, 2021). "Here, we observed significantly increased transcription of both MUC2 and TFF3 in cells derived from human colonic epithelial cell line HT-29/B6 immediately after C. jejuni NCTC 11168 infection." (PMID 34183045, 2021). "C. jejuni 81–176 infection resulted in a pronounced decrease of TFF3 transcription when compared to naïve controls (0.38-fold change, P ≤ 0.0001), whereas the MUC2 transcription was slightly decreased upon infection (0.80-fold change, P ≤ 0.05)." (PMID 34183045, 2021). "The relative fold differences of MUC2 and TFF3 mRNA levels were calculated and revealed an approximately 2-fold up-regulation (P ≤ 0.01) of both factors relatively early (i.e., 1 h) post infection (p.i.)." (PMID 34183045, 2021). "MUC2 and protocadherin 24 (PCDH24) are targeted by EHEC at early stages of infection.EHEC reduces colonic mucus and affects the brush border cytoskeleton in the absence of commensal bacteria." (PMID 33544117, 2021). "Compared to uninfected cells, HMPV infection induced a significant fold-increase expression of MUC1 (8.3 ± 2), MUC2 (43.4 ± 13), MUC4 (54 ± 12), MUC5ac (23.3 ± 11.5) and MUC19 (77 ± 35), while no significant induction of MUC15, MUC16 and MUC20 was observed." (PMID 32899224, 2020). "PLD photoperiod treatment reduced baseline mRNA levels of our mucosal immunity marker, the Mucin-2 gene muc2, in skin tissues of all PLD fish and reversed the pattern of upregulation observed in PSD fish in response to infection." (PMID 32605431, 2020). "Because staining for the goblet cell marker, mucin 2 (Muc2), was incompatible with the ISH procedures, we stained serial tissue sections and confirmed the virus’ selective infection of goblet cells." (PMID 32350281, 2020). "IECs have been shown to differentiate into goblet cells following infection with T. muris in response to TH2 cell-derived cytokines and produce effector molecules such as the mucins Muc5AC and Muc2, cytokines such as TSLP as well as the small protein RELMβ." (PMID 27598373, 2016). "After infection with E. coli K99, the expression of P. pentosaceus SNF15, Claudin-1, MUC2, and ZO-1 in oral administration increased significantly compared with the CN group (p < 0.05), and the expression level of occludin did not change significantly (p > 0.05)." (PMID 40151573, 2025). "Furthermore, infection appeared to disrupt goblet cell maturation or secretion, as indicated by increased periodic acid–Schiff (PAS) staining alongside decreased MUC2 production." (PMID 41395236, 2025). "Infection with ST decreased the proliferation genes PCNA, Ki67, and Cyclin; the ISC marker gene Lgr5; the quiescent ISC marker gene Bmi1; the Goblet cell marker gene Muc2; the Paneth cell marker gene Lyz1; and Wnt3a mRNA levels (p < 0.05)." (PMID 38540864, 2024). "Administration of the probiotic as well as infection with S. Infantis did not modify transcript abundance of muc-2 (p > 0.05)." (PMID 36838221, 2023).